RPL11 (ribosomal protein L11)
Description:
Component of the ribosome, a large ribonucleoprotein complex responsible for the synthesis of proteins in the cell. The small ribosomal subunit (SSU) binds messenger RNAs (mRNAs) and translates the encoded message by selecting cognate aminoacyl-transfer RNA (tRNA) molecules. The large subunit (LSU) contains the ribosomal catalytic site termed the peptidyl transferase center (PTC), which catalyzes the formation of peptide bonds, thereby polymerizing the amino acids delivered by tRNAs into a polypeptide chain. The nascent polypeptides leave the ribosome through a tunnel in the LSU and interact with protein factors that function in enzymatic processing, targeting, and the membrane insertion of nascent chains at the exit of the ribosomal tunnel. As part of the 5S RNP/5S ribonucleoprotein particle it is an essential component of the LSU, required for its formation and the maturation of rRNAs. Promotes nucleolar location of PML (By similarity).
Synonyms: L11; uL5; DBA7; GIG34
Tractability: Small molecule: an approved drug acts on it; a structure with a bound ligand is known; a high-quality ligand is known. PROTAC: UniProt records ubiquitination sites on it; ubiquitination databases record sites on it; its protein half-life has been measured; a small molecule that binds it is known. Other modalities: a drug acting on it is in phase 2 or 3 trials.
Target class: Other cytosolic protein
Gene: Protein-coding gene on chromosome 1 (23,691,685 to 23,696,835, forward strand). Ensembl gene ENSG00000142676.
Subcellular location: Nucleus, nucleolus; Cytoplasm
Pathways (Reactome):
Metabolism of proteins: Eukaryotic Translation Termination; Formation of a pool of free 40S subunits; GTP hydrolysis and joining of the 60S ribosomal subunit; L13a-mediated translational silencing of Ceruloplasmin expression; PELO:HBS1L and ABCE1 dissociate a ribosome on a non-stop mRNA; Peptide chain elongation; Ribosome Quality Control (RQC) complex extracts and degrades nascent peptide; SRP-dependent cotranslational protein targeting to membrane; ZNF598 and the Ribosome-associated Quality Trigger (RQT) complex dissociate a ribosome stalled on a no-go mRNA
Metabolism of RNA: Major pathway of rRNA processing in the nucleolus and cytosol; Nonsense Mediated Decay (NMD) enhanced by the Exon Junction Complex (EJC); Nonsense Mediated Decay (NMD) independent of the Exon Junction Complex (EJC)
Cellular responses to stimuli: Response of EIF2AK4 (GCN2) to amino acid deficiency
Developmental Biology: Regulation of expression of SLITs and ROBOs
Disease: Viral mRNA Translation
Metabolism: Selenocysteine synthesis
Gene Ontology:
Molecular function: 5S rRNA binding; protein binding; RNA binding; structural constituent of ribosome; ubiquitin ligase inhibitor activity; ubiquitin protein ligase binding
Biological process: cytoplasmic translation; negative regulation of ubiquitin-dependent protein catabolic process; protein targeting; ribosomal large subunit assembly; ribosomal large subunit biogenesis; rRNA processing; negative regulation of myoblast fusion; negative regulation of proteasomal ubiquitin-dependent protein catabolic process; protein localization to nucleus; spermatogenesis; striated muscle contraction; translation
Cellular component: cytoplasm; cytosolic large ribosomal subunit; cytosolic ribosome; extracellular exosome; membrane; nucleolus; nucleoplasm; protein-containing complex; cytosol; ribosome
Genetic constraint (gnomAD): Loss-of-function variants: 3 observed, 22.65 expected, observed/expected ratio (o/e) 0.13, 90% interval 0.059 to 0.34. The synonymous counts are far from expectation, so gnomAD's model fits this gene poorly and the ratio says little. Missense variants: 146 observed, 224 expected, observed/expected ratio (o/e) 0.65, 90% interval 0.57 to 0.75. Synonymous variants: 96 observed, 73.49 expected, observed/expected ratio (o/e) 1.31, 90% interval 1.11 to 1.55.
Homologues: Orthologues: chimpanzee RPL11 (100% identical), mouse Rpl11 (100% identical), guinea pig RPL11 (99% identical), zebrafish rpl11 (97% identical), tropical clawed frog rpl11 (92% identical), rat Rpl11 (90% identical), Drosophila melanogaster RpL11 (82% identical), Caenorhabditis elegans rpl-11.2 (79% identical), Caenorhabditis elegans rpl-11.1 (79% identical), pig RPL11 (72% identical).
Diseases named in the same sentence as RPL11 in open-access papers:
RPL11 is named in the same sentence as 63 diseases in open-access papers, as found by Europe PMC text mining. Sharing a sentence is not in itself a finding about the gene and the disease. The quoted sentences say what the papers report.
Diamond-Blackfan anemia (25 papers, 2010 to 2024). A congenital aregenerative and often macrocytic anemia with erythroblastopenia. "The haploinsufficiency of functional uL5, resulting from mutations in the RPL11 gene, has also been identified as a common cause of Diamond-Blackfan anemia (DBA); to date, 32 mutations in this gene have been described that occur in patients with DBA." (PMID 34948282, 2021). "For example, mutations in RpS19, RpS17, RpS24, RpL35a, RpS7, RpL5, RpL11, RpS10 and RpS26 have been associated with the human disease Diamond Blackfan Anemia (DBA), a dominant autosomal bone marrow failure syndrome, characterised by hypoplastic anemia with a predisposition to leukemia." (PMID 22194697, 2011). "There are abundant genetic and experimental evidences demonstrate that Diamond-Blackfan anemia (DBA), a dominant autosomal bone marrow failure syndrome, is due to mutations in ribosomal genes including RPS19, RPS24, RPL5, RPL11, and RPS29, etc8-12." (PMID 31523176, 2019). "In humans, mutations in RPs have been implicated in hematopoetic disorders, most notably Diamond-Blackfan anemia (DBA), which has been attributed to mutations in RPS19, RPS26, RPS24, RPS17, RPS10, RPS7, RPL35a, RPL26, RPL11, and RPL5." (PMID 23382688, 2013). "One notable syndrome is Diamond-Blackfan anemia (DBA) caused by mutations in ribosomal proteins (RPS19, RPL11, RPL5 and others) leading to defective 40S or 60S ribosomal subunit production with elevated risk of leukemia and osteosarcoma." (PMID 21152184, 2011). "Furthermore, IACS-010759 upregulates the expression of ribosomal protein genes such as RSP27, RPL11, RPL32, RPL35A, and RPL11, mutations which are found in osteosarcoma-prone Diamond-Blackfan anemia (DBA) patients." (PMID 34965247, 2021). "For example, the Diamond-Blackfan Anemia (DBA) is caused by heterozygous loss-of-function mutations in genes encoding RPs, such as RPS19, RPL5, and RPL11, while the 5q-syndrome is caused by a somatically acquired deletion of chromosome 5q, which leads to haploinsufficiency of RPS14." (PMID 30862090, 2019). "Congenital heterozygous inactivating mutations and deletions affecting RPL5, RPL11 and RPS15 have also been described in Diamond Blackfan Anemia (DBA), a congenital syndrome belonging to a family of human disorders, ribosomopathies, caused by impaired ribosome biogenesis and function." (PMID 28147343, 2017). "Further, mutations in several ribosomal protein (RP) genes, such as RPS19, RPL5, RPL11, RPL35A, RPS10, RPS17, and RPS24, cause Diamond-Blackfan anemia (DBA)." (PMID 38820160, 2024). "For instance, studies in Diamond-Blackfan anemia (DBA) demonstrated that mutations in 60S or 40S ribosomal proteins [such as RPL5, RPL11, RPS7, RPS10 among others] decrease the ribosome levels but leave the composition of the ribosomes intact." (PMID 30697227, 2018). "Defects in several ribosomal proteins including RPS19, RPL11 and RPS14 have been observed in two types of anemia: Diamond Blackfan Anemia and 5q- syndrome." (PMID 31619461, 2019). "The patient tested negative for pathogenic variants in genes associated with Diamond-Blackfan anemia: RPS19, RPL5, RPL11, RPS26, RPL35a, and RPL15." (PMID 35774100, 2022). "The most well characterized is Diamond Blackfan anemia (DBA), which results from haploinsufficiencies in several different RP genes (RPS24/eS24, RPS17/eS17, RPL35A/eL33, RPL5/uL18, RPL11/uL5, RPS7/eS7, RPL36/eL36, RPS15/uS19, RPS27A/eS31) and RPS19/eS19, which is mutated in 25% of patients." (PMID 33565275, 2021).
breast carcinoma (20 papers, 2017 to 2025). "The purpose of this research is to elucidate the intricate molecular interactions among SNORA47, EBF3, and RPL11 in breast cancer cells." (PMID 40264043, 2025). "Meanwhile, another Team Ang Zheng found that SNORA47 affected stemness and chemotherapy sensitivity of Luminal breast cancer cells via EBF3/RPL11/c-Myc axis, providing a new direction for precision therapy of Luminal breast cancer patients." (PMID 40567603, 2025). "Previous research has demonstrated a correlation between high levels of expression of RPL11 and improved overall survival rates in breast cancer patients." (PMID 36984424, 2023). "Our results indicated that overexpression of RPL11 or RPL5 suppressed breast cancer cell proliferation, blocked G1–S cell-cycle transition, and induced cancer cell apoptosis." (PMID 32483207, 2020). "In this study, TCGA data revealed that RPL11 and RPL5 expression was significantly lower in breast cancer tissues, and their expression levels were associated with overall survival." (PMID 32483207, 2020). "To this end, we suspected that SNORA47 may affect the nucleolus-nucleplasm translocation of RPL11, which in turn promotes c-Myc expression to influence stemness and drug sensitivity of breast cancer cells." (PMID 40264043, 2025). "Additionally, our study revealed an interaction between EBF3 and RPL11 in breast cancer cells through Co-IP analysis." (PMID 40264043, 2025).
breast carcinoma (continued). "Herein, we showed that changes in the translocation of RPL11 in the nucleolus and nucleoplasm may affect changes in c-Myc expression, which in turn affects the stemness phenotype of breast cancer cells." (PMID 40264043, 2025). "Furthermore, RRS1 may augment breast cancer cell invasion and metastasis via the RPL11-c-Myc-SNAIL axis." (PMID 37090698, 2023). "Contradicting our results, previous studies have shown that low expression levels of ribosomal proteins RPS9, RPS14, RPS27, RPL11 and RPL14 are related to a poor overall survival in breast cancer patients, especially in TNBC." (PMID 37888706, 2023). "In a previous report, Fang and Zhang used integrated bioinformatics analyses and identified that low mRNA expression of RPL11, RPS14, RPS9, and RPL10A were related to a worse overall survival of breast cancer patients." (PMID 33718123, 2021). "It was found that both RPL11 and RPL5 expression levels were significantly lower in breast cancer tissues (n = 1099) than in normal breast tissues (n = 113)." (PMID 32483207, 2020). "To further explore the biological effect of RPL11 and RPL5 in breast cancer, we analyzed their expression using TCGA data." (PMID 32483207, 2020). "TCGA data revealed significantly lower RPL11 and RPL5 expression in breast cancer tissues; additionally, overexpression of RPL11/RPL5 significantly suppressed breast cancer cell proliferation and G1–S cell cycle transition and induced apoptosis in vitro." (PMID 32483207, 2020). "We identify RPSA, RPS5, RPS20, RPL5, RPL11 and RPL23A as six interesting cancer driver candidates and show a tumor suppressor role for RPL5 in the context of breast cancer." (PMID 28147343, 2017). "Therefore, SNORA47 affected the stemness phenotype of breast cancer cells by influencing the interactions between EBF3 and RPL11, which consequently influenced the stemness phenotype and sensitivity of the breast cancer cells." (PMID 40264043, 2025). "However, the changes in the expression of RPL11 in the nucleolus and nucleoplasm persisted after overexpression of EBF3 in SNORA47-silenced-expressing breast cancer cells." (PMID 40264043, 2025).
lymphoma (8 papers, 2013 to 2023). A malignant (clonal) proliferation of B- lymphocytes or T- lymphocytes which involves the lymph nodes, bone marrow and/or extranodal sites. "RPL11 is involved in gastric cancer, colorectal cancer, fibroblasts, lymphoma, and esophageal squamous carcinoma, where it acts as a cancer suppressor gene." (PMID 32483207, 2020). "In support of this notion, RPL11 (uL5) and RPL22 (eL22) inactivation shortens the latency of lymphoma development in mouse models and is associated with c-MYC upregulation." (PMID 30862070, 2019). "The relative mRNA expression levels of 4 ribosomal protein genes that were up-regulated in CUP (RPS7, RPL11, RPS10, and RPL36) were compared with the levels in normal lymphoma and 24 known cancer types." (PMID 23671674, 2013). "Although RPL11 has not been reported as a cancer suppressor gene in ovarian cancer studies, it is involved in the development of gastric cancer, colorectal cancer, fibroblasts, lymphoma, and esophageal squamous carcinoma." (PMID 37124501, 2023).
colorectal cancer (7 papers, 2018 to 2025). A primary or metastatic malignant neoplasm that affects the colon or rectum. "Further, in the colorectal cancer study, aspirin decreases RpS6 expression compared to RpL11; this misbalance in ribosomal proteins impairs ribosome maturation." (PMID 36875757, 2023). "Similar to our findings, Ribosomal Protein L11 (RPL11) has been identified to play a role in various cancers such as esophageal squamous carcinoma, fibroblasts, colorectal cancer, and gastric cancer." (PMID 39891297, 2025).
hepatocellular carcinoma (7 papers, 2021 to 2025). A malignant tumor that arises from hepatocytes. "For example, the upregulation of SNORA18L5 in hepatocellular carcinoma (HCC) led to hyperactive ribosome biogenesis, increasing levels of mature rRNAs that in turn caused the accumulation of the ribosomal proteins RPL5 and RPL11 in the nucleolus." (PMID 34638533, 2021).